AMBN (ameloblastin)
Description:
Involved in the mineralization and structural organization of enamel.
Synonyms: AI1F
Tractability: Antibody: UniProt places it where antibodies can reach, with medium confidence; UniProt predicts a signal peptide or a membrane-spanning region; its Gene Ontology location is reachable by antibodies, with medium confidence.
Gene: Protein-coding gene on chromosome 4 (70,592,256 to 70,607,288, forward strand). Ensembl gene ENSG00000178522.
Subcellular location: Secreted, extracellular space, extracellular matrix
Subcellular location (Human Protein Atlas): Vesicles; Nucleoplasm; Predicted to be secreted
Pathways (Reactome):
Metabolism of proteins: Post-translational protein phosphorylation; Regulation of Insulin-like Growth Factor (IGF) transport and uptake by Insulin-like Growth Factor Binding Proteins (IGFBPs)
Gene Ontology:
Molecular function: protein binding; growth factor activity; structural constituent of tooth enamel
Biological process: cell adhesion; regulation of cell population proliferation; odontogenesis of dentin-containing tooth; signal transduction
Cellular component: endoplasmic reticulum lumen; non-collagenous component of interstitial matrix
Genetic constraint (gnomAD): Loss-of-function variants: 34 observed, 33.66 expected, observed/expected ratio (o/e) 1.01, 90% interval 0.77 to 1.35. The upper end of that interval is the gene's LOEUF score, 1.35, which puts it in group 5 of 6, group 1 being the genes least tolerant of losing a copy. Missense variants: 491 observed, 486.51 expected, observed/expected ratio (o/e) 1.01, 90% interval 0.94 to 1.09. Synonymous variants: 167 observed, 169.86 expected, observed/expected ratio (o/e) 0.98, 90% interval 0.87 to 1.12.
Homologues: Orthologues: chimpanzee AMBN (99% identical), macaque AMBN (89% identical), dog AMBN (71% identical), rabbit AMBN (68% identical), pig AMBN (67% identical), mouse Ambn (62% identical), rat Ambn (60% identical), guinea pig AMBN (58% identical), tropical clawed frog ambn (32% identical).
Diseases named in the same sentence as AMBN in open-access papers:
AMBN is named in the same sentence as 27 diseases in open-access papers, as found by Europe PMC text mining. Sharing a sentence is not in itself a finding about the gene and the disease. The quoted sentences say what the papers report.
amelogenesis imperfecta (10 papers, 2009 to 2025). Amelogenesis imperfecta (AI) represents a group of developmental conditions affecting the structure and clinical appearance of the enamel of all or nearly all the teeth in a more or less equal manner, and which may be associated with morphologic or biochemical changes elsewhere in the body. "AMBN gene (4q13.3), containing 13 exons was discovered as the causative gene for non-syndromic autosomal recessive amelogenesis imperfecta." (PMID 37228816, 2023). "Although AMBN has long been a candidate gene for the etiology of amelogenesis imperfecta (AI), only two AI‐causing AMBN defects have been reported to date." (PMID 31402633, 2019). "As the second most significant enamel matrix protein, AMBN is associated with amelogenesis imperfecta when mutated." (PMID 40271211, 2025). "Given these various findings, we predict that AMBN is an excellent candidate for enamel genetic disease, amelogenesis imperfecta (AI)." (PMID 26223266, 2015). "Ameloblastin deficiency results in severe enamel hypoplasia with lots of prism structure in mouse models, although no human mutations have yet been described in amelogenesis imperfecta patients." (PMID 19913215, 2009). "For some other genes encoding for enamel matrix proteins, e.g. ameloblastin (AMBN 4q 11), tuftelin (TUFT1 1q 21) and amelotin (4q 13.3) mutations have not yet been identified in patients with amelogenesis imperfecta." (PMID 19913215, 2009). "In humans, AMBN is located on the long arm of chromosome 4 (4q13-21), containing the gene locus for the autosomal dominant hypoplastic form of AIH2, that affects enamel formation and is the most prevalent amelogenesis imperfecta (AI) type (85 % of all inherited AI)." (PMID 26223266, 2015).
ameloblastoma (7 papers, 2012 to 2025). The most common odontogenic tumor, arising from the epithelial component of the embryonic tooth and usually affecting the molar-ramus region of the mandible or maxilla. "Three missense and one splicing site mutations affecting the ameloblastin gene (AMBN) were found in 4/4 ameloblastomas by direct sequencing." (PMID 35048068, 2021). "Mutation of AMBN (ameloblastin) gene has been found in CEOT as well as other tumors of odontogenic epithelium including ameloblastoma, adenomatoid odontogenic tumor and squamous odontogenic tumor, suggestive of a role of this mutation in tumorigenesis of the group of odontogenic tumors." (PMID 30771214, 2019). "This discrepancy between mRNA and protein expressions, as well as the limited or inconsistent expression of enamel-related proteins (particularly ameloblastin), suggests that ameloblastomas may exhibit a diverse range of differentiation." (PMID 39937015, 2025). "The ameloblastin (AMBN) gene is strongly expressed by ameloblasts and weakly expressed by odontoblasts and preodontoblasts, with moderate expression also observed in Hertwig's epithelial root sheath and odontogenic benign tumors with malignant behavior such as ameloblastoma." (PMID 39299262, 2025). "A previous study revealed that overexpression of AMBN in human ameloblastoma inhibited proliferation through suppression of negative cell cycle regulators including p21Cip1 and p27Kip1." (PMID 23372724, 2013).
dental caries (7 papers, 2017 to 2024). The decay of a tooth, in which it becomes softened, discolored, and/or porous. "Several previous studies have identified an association between several genes and dental caries, including genes related to enamel formation such as AMBN, AMELX, and ENAM; taste receptor genes such as TAS2R38, TAS1R2; immune-related genes such as HLA; and saliva genes such as MUC5B, PRH1." (PMID 38414691, 2024). "Genetic association studies of dental caries have suggested that caries may be influenced by variations in enamel formation genes, such as ameloblastin (AMBN), amelogenin (AMELX), enamelin (ENAM), matrix metalloproteinase 20 (MMP20), tuftelin (TUFT1), and tuftelin-interacting protein 11 (TFIP11)." (PMID 29163197, 2017). "The AMBN rs4694075 gene that controls enamel crystals’ elongation process and contributes to enamel mineralization during tooth development is involved in the initiation of dental caries in patients with asthma." (PMID 33541418, 2021). "In this case–control study, 15 SNPs in ALOX15, AMBN, AMELX, KLK4, TFIP11, and TUFT1 genes were analyzed in 150 children with primary dentition and 611 children with permanent teeth with/without dental caries from the European Longitudinal Study of Pregnancy and Childhood (ELSPAC) cohort." (PMID 36422720, 2023).
odontogenic tumors (4 papers, 2017 to 2021). "AMBN-deficient mice exhibit severe enamel hypoplasia and the formation of odontogenic tumors." (PMID 34630166, 2021). "Different carcinomas have amyloid stroma, and odontogenic tumors are positive for thioflavin T and Congo Red staining and are also immunopositive for the enamel matrix protein ameloblastin." (PMID 31137462, 2019). "In a previous study, AMBN inhibited proliferation of odontogenic tumor cells through the up-regulation of p21 and p275; therefore, we also analyzed the relation between AMBN and p21 in osteosarcoma." (PMID 28054649, 2017). "Mutant mice expressing a truncated form of AMBN lacking portions of the protein encoded by exons 5 and 6 develop soft tissue tumors in the buccal vestibule of the maxilla with age4, and AMBN plays an important role in preventing odontogenic tumor development by suppressing cell proliferation." (PMID 28054649, 2017).
dental fluorosis (3 papers, 2019 to 2022). A condition that results from excessive fluoride ingestion during tooth development, resulting in tooth discoloration ranging from white streaks to brown stains and cracks or pits in the tooth enamel. "This coincides with the results of another study, which showed that AMBN gene might serve as the susceptibility factors causing the coal-fired fluorosis in a Chinese population." (PMID 36354656, 2022).
osteosarcoma (3 papers, 2015 to 2024). A usually aggressive malignant bone-forming mesenchymal neoplasm, predominantly affecting adolescents and young adults. "For instance, inhibition of the SRC/STAT3 signaling pathway by ameloblastin was shown to induce apoptosis and suppress chemoresistance of osteosarcoma cells." (PMID 38086608, 2024). "Using this antibody, we examined AMBN expression in primary osteosarcoma cases using immunohistochemical analysis." (PMID 28054649, 2017). "Here we demonstrated that stable overexpression of AMBN induced apoptosis and suppressed colony formation and cell migration via the inactivation of Src-Stat3 pathway in human osteosarcoma cells." (PMID 28054649, 2017). "Our findings suggest that AMBN can be a new prognostic marker and therapeutic target for osteosarcoma combined with conventional doxorubicin treatment." (PMID 28054649, 2017). "Osteosarcoma with pulmonary metastases still shows a poor prognosis; therefore, AMBN can be a useful prognostic marker and a target for the treatment of the patients with osteosarcoma when combined with conventional doxorubicin treatment." (PMID 28054649, 2017). "First, AMBN expression among human osteosarcoma cell lines was examined." (PMID 28054649, 2017). "Indeed, immunohistochemical expression of AMBN was significantly correlated with better outcome of osteosarcoma patients." (PMID 28054649, 2017). "Finally, We assessed AMBN expression in human primary osteosarcoma cases and its correlation with lung metastasis and prognosis." (PMID 28054649, 2017). "Importantly, in this study we demonstrated that in cases of osteosarcoma with positive AMBN expression, there are lower frequency of pulmonary metastases and better prognosis." (PMID 28054649, 2017). "Here, we examined the tumor suppressive role of AMBN in osteosarcoma cells." (PMID 28054649, 2017). "Positive AMBN expression was observed in 16 out of 37 osteosarcoma cases." (PMID 28054649, 2017). "Therefore, we hypothesized that AMBN functions as a tumor suppressor in osteosarcoma through the inhibition of Src and its downstream Stat3 activities." (PMID 28054649, 2017). "In this study, the activation of Src-Stat3 signaling was observed among all tested human osteosarcoma cell lines, except NOS-1 cells that highly express AMBN." (PMID 28054649, 2017). "Interestingly, osteosarcoma cases with positive AMBN expression showed better prognosis than those without, but the difference in prognosis was not statistically significant as determined by Log-rank test." (PMID 28054649, 2017). "Furthermore, ectopic expression of Fam20A in the human osteosarcoma cell line U2OS, which produces Fam20C, but not Fam20A, significantly increased phosphorylation of V5-tagged OPN, ENAM and AMBN, without altering Fam20C expression levels." (PMID 25789606, 2015).
enamel hypoplasia (2 papers, 2015 to 2020). "We had also identified novel genes from tooth germ complementary DNA library, namely Ameloblastin (Ambn), Epiprofin (Epfn), and AmeloD, and each of these knockout mice models showed severe enamel hypoplasia." (PMID 32984333, 2020).
prostate carcinoma (2 papers, 2021 to 2023). A carcinoma that arises from epithelial cells of the prostate gland. "It was however demonstrated that AMBN was among four factors that were potential independent prognostic factors for prostate cancer." (PMID 37388244, 2023). "A ceRNA network analysis of prostate cancer established a network consisting of four hub genes, homeobox B5 (HOXB5), glypican 2 (GPC2), pepsinogen A-5 (PGA5), and ameloblastin (AMBN), which are strongly associated with patient survival." (PMID 34681112, 2021).
calcifying epithelial odontogenic tumor (1 paper, 2015). A slow growing, locally invasive neoplasm arising from tooth-forming tissues. "In humans and some mammals, amyloidosis has been associated with calcifying epithelial odontogenic tumors (CEOT) and AMBN was found to be highly expressed in these cells." (PMID 26223266, 2015).
dentinogenesis imperfecta (1 paper, 2024). Dentinogenesis imperfecta (DGI) is a hereditary dentin defect characterized by abnormal dentin structure resulting in abnormal tooth development. "A report of a large dominant family where AI and dentinogenesis imperfecta (DI) segregated with a heterozygous AMBN missense variant p.(Pro357Ser) challenged our understanding of AMBN-associated disease." (PMID 38058155, 2024).
enamel-renal syndrome (1 paper, 2021). "While mutations in AMBN and ACP4 cause non-syndromic autosomal recessive hypoplastic AI, mutations in FAM20A cause syndromic autosomal recessive hypoplastic AI (enamel-renal syndrome, OMIM#204690)." (PMID 33652941, 2021).
gastric cancer (1 paper, 2023). A primary or metastatic malignant neoplasm involving the stomach. "Another AMBN promoter analysis identified SP6, later suggested to be among the genes implicated in gastric cancer together with MEF2, which resulted from our own AMBN promoter analysis." (PMID 38020879, 2023).
ovarian serous adenocarcinoma (1 paper, 2023). An adenocarcinoma that arises from the ovary and is characterized by the presence of malignant epithelial cells that, in well differentiated tumors, resemble the epithelium of the fallopian tube or, in poorly differentiated tumors, show anaplastic features and marked nuclear atypia. "In our multifactorial Cox analysis, AMBN was shown to be one of the independent prognostic factors for ovarian serous adenocarcinomas." (PMID 37388244, 2023).
testicular cancer (1 paper, 2022). A primary or metastatic malignant neoplasm that affects the testis. "It has been demonstrated that increased oestrogen production is associated with reduced spermatogenesis in men with testicular cancer, and perhaps AMBN levels may indirectly reflect reduced spermatogenesis in men with testicular cancer after treatment." (PMID 35454778, 2022).
testicular germ cell tumour (1 paper, 2022). "We validated ameloblastin’s expression in testicular tissue, and used comprehensive bioinformatics analysis of 156 patients with testicular germ cell tumour to show that the level of ameloblastin was associated with the time of tumour recurrence after the first cure." (PMID 35454778, 2022).
uterine carcinosarcoma (1 paper, 2022). A usually aggressive malignant neoplasm arising from the uterine corpus and less often the cervix. "AMBN mRNA expression was only found to be present in kidney chromophobe (KICH), uterine carcinosarcoma (UCS) tissues and TGCT, as well as in normal testicular tissue, and not transcribed in the other 29 cancer tissues and their corresponding normal tissues analysed." (PMID 35454778, 2022).
tumor (9 papers, 2015 to 2025). "Ameloblastin is identified as an extracellular matrix protein and has shown to be associated with tumour progression." (PMID 35454778, 2022). "However, in the survival analysis of progress free interval (PFI) in all TGCT patients, we found that low levels of AMBN were associated with longer intervals between tumour recurrences after the initial cure." (PMID 35454778, 2022). "Interestingly, human ameloblastoma, a benign but destructive tumor, expresses AMBN transcripts with tumor-specific mutations." (PMID 26223266, 2015). "The function of the heparin structural domain of AMBN has recently been investigated in the proliferation of enucleated cell tumours." (PMID 35454778, 2022). "Based on the observed differences in PFI in tumour tissues with respect to AMBN mRNA level, a natural follow-up was to investigate its role and putative effect." (PMID 35454778, 2022). "In further prognostic analyses targeting different subgroups of clinical information classification, patients who developed lymphatic invasion metastases and had low levels of AMBN in tumour tissue were found to have longer cancer recurrence intervals." (PMID 35454778, 2022). "Compared to normal testicular tissue, AMBN levels were decreased in tumour tissue." (PMID 35454778, 2022). "Src/STAT3 signalling in OS may be deactivated by tumour suppressor effect from enamel matrix protein, ameloblastin (AMBN), representing a potential biomarker and therapeutic target for OS." (PMID 33382511, 2021). "The expression of CDK1, -4, and -6 was not changed in AM-1 cells, even with the induced overexpression of ameloblastin gene that may function as a tumor suppressor." (PMID 28357197, 2016). "Among odontogenesis related genes, AMBN is specifically expressed in T3, other genes including ENAM, AMELX and AMELY are not expressed in all the tumor cells." (PMID 39223689, 2024).
cancer (2 papers, 2019 to 2022). A tumor composed of atypical neoplastic, often pleomorphic cells that invade other tissues. "We investigated the relationship between the expression level of AMBN mRNA and several clinical factors/results in TGCT patients to identify the clinical significance of AMBN in this cancer." (PMID 35454778, 2022). "The TCGA and GTEx databases were used to investigate the expression of AMBN mRNA in various normal and cancers tissues." (PMID 35454778, 2022). "In addition, analysis of AMBN mRNA levels for different clinical stages suggested that patients with intermediate to advanced TGCT had significantly lower levels of AMBN in their cancer tissues than patients with earlier stages." (PMID 35454778, 2022). "If AMBN is expressed during spermatogenesis, a reduction in AMBN may be due to cancer-induced changes in cell differentiation, tissue infiltration, or other changes in the cellular micro-environment." (PMID 35454778, 2022). "In conclusion, we found that AMBN could be a novel predictor of cancer recurrence for TGCT." (PMID 35454778, 2022). "Interestingly, in TGCT patients without concomitant lymphatic invasion, mRNA levels of AMBN did not correlate with the time to cancer recurrence after the first treatment." (PMID 35454778, 2022).
genetic disease (1 paper, 2015). "They cannot be changed otherwise the AMBN function linked to this position will be disturbed and will result in a genetic disease with apparent enamel disorder." (PMID 26223266, 2015). "We performed evolutionary analyses of AMBN in order to (i) identify residues and motifs important for the protein function, (ii) predict mutations responsible for genetic diseases, and (iii) understand its molecular evolution in mammals." (PMID 26223266, 2015). "Because of its important role in mammalian enamel formation, for long AMBN has been considered a candidate gene for amelogenesis imperfecta hereditary type 2 (AIH2), a human genetic disease." (PMID 26223266, 2015).
AMBN also shares sentences with these, for which no sentence is quoted: asthma (2 papers); chronic periodontitis (2); adenomatoid odontogenic tumor (1); gestational diabetes (1); ovarian carcinoma (1); soft tissue tumors (1); squamous odontogenic tumor (1); vitamin D deficiency (1).